RAB25 (RAB25, member RAS oncogene family)
Diseases named in the same sentence as RAB25 in open-access papers (continued):
Sharing a sentence is not in itself a finding about the gene and the disease.
cancer (continued). "Treatment of cancer cell lines in which RAB25 is pro-oncogenic with an optimized stapled peptide, RFP14, inhibits migration, and proliferation in a RAB25-dependent manner." (PMID 28939823, 2017). "The correlation of Rab25/CLIC3 expression and clinical outcome in different types of cancer has to be investigated." (PMID 28969096, 2017). "Hence, the ability of Rab25 to increase OPG expression in a subset of cancer cell lines and to increase OPG release by the majority of cancer cell lines assessed, suggests that amplification of Rab25 may provide survival advantages for cancer cell independent of TRAIL and RANKL." (PMID 25520884, 2013). "Because we have found that CLIC3 acts to recycle integrins that have been targeted to late endosomes/lysosomes by the action of Rab25, we wished to evaluate the expression of CLIC3 in cancers thought to be driven by Rab25." (PMID 22197222, 2012). "Cancer stem cells can be critically dependent on the HIF-1 alpha pathway, and the effects of Rab25 may in part be controlling the stemness of the cells." (PMID 38803515, 2024). "The significant conflict between the functions of Rab25 in promoting or inhibiting cancer progression in different cancer types might be due to the involvement CLIC3, which is needed for RAB25-regulated integrin transport." (PMID 34141705, 2021). "Independent of EMT, RAB25 has gained attention because its expression is altered in different human cancer subtypes, but its role in cancer progression is not clear." (PMID 30445998, 2018). "One of the hypotheses suggested that the role of Rab25 depends on its ability to induce chloride intracellular channel protein 3 (CLIC3), which is involved in α5β1 integrin trafficking necessary for cancer cell invasion." (PMID 28969096, 2017). "Statistically, the IRS of Rab25 protein showed a significant increase in PCa tissues compared with adjacent non-cancerous prostate tissues (cancer vs. normal: 5.43 ± 2.75 vs. 1.65 ± 1.26, P < 0.001)." (PMID 28400705, 2017). "Mechanistically, Rab25 expression promotes anti-apoptotic phosphoinositide 3-kinase (PI3K)-Akt pathway and inhibits pro-apoptotic molecules expression such as BAK thereby increasing aggressiveness of cancer cells." (PMID 27716280, 2016). "Interestingly, levels of both RAB25 and ESRP1 mRNA were high when ZEB1 mRNA levels were low and vice versa, which is consistent with a previous report examining other cancers." (PMID 26646320, 2016). "Similarly, in cancer cells, CLIC3 in the late endosome/lysosome compartment works with Rab25 to facilitate recycling of fibronectin binding integrins from late endosome/lysosome to plasma membrane." (PMID 27113959, 2016). "Both RAB25 and ESRP1 are strongly downregulated by the expression of ZEB1, the epithelial-mesenchymal transition (EMT) inducer, in a Tetracycline induced model of human cancer." (PMID 26646320, 2016). "It was, however, noticeable that the RAB25 gene was not selected in this test, while it was, when we compared mean expression levels in cancer cell lines to that in a series of 5 normal breast tissues expression (t test p value=0.002)." (PMID 17060936, 2006). "However, the lysosomal integrin beta 1 could be promoted to recycling from late endosomes or lysosomes by Rab25 and CLIC3 to drive cancer progression." (PMID 29707067, 2018). "Although EGF–EGFR signaling is only one of several pathways involved in cancer cell proliferation and motility, the respective effects of EGF and Rab25 on integrin localization revealed in the present study may partially explain the diverse effects of EGFR-targeting drugs." (PMID 29515334, 2018). "Furthermore, a highly significant reverse correlation between RAB25 and ZEB2 expression in several human cancer types could be identified." (PMID 30445998, 2018).
cancer (continued). "Furthermore, the moderately or strongly positive immunostainings of Rab25 protein were observed in the cytoplasm of cancer cells in PCa tissues, while there was only weak or negative immunostainings of Rab25 protein shown in adjacent non-cancerous prostate tissues." (PMID 28400705, 2017). "As far as we are aware, RAB25 and CYP4B1 have been reported to be related to carcinomas, but it is not clear how the promoter methylations and mRNA expressions of RAB25 and CYP4B1 behave in ccRCC15,16." (PMID 29079774, 2017).
tumor (64 papers, 2008 to 2025). "Rab25 is a tumor suppressor in the intestine, and when crossed over in apc-deficient mice, it increases the tumor formation frequency." (PMID 37998722, 2023). "It demonstrated that expression of RAB25 is associated with tumor progression, and loss of RAB25 leads to cell migration and invasion." (PMID 34868916, 2021). "Loss of Rab25 is common in colorectal cancer and head and neck squamous cell carcinomas, where it appears to act as a tumour suppressor gene." (PMID 32842549, 2020). "Direct interaction between Rab25 and α5β1 integrin was linked to increase tumor cell metastasis and aggressiveness." (PMID 28969096, 2017). "Rab25-deficient mice have more tumor formation and less β1 integrin recycled to the lateral membrane." (PMID 28969096, 2017). "Up till now, the cause of hypermethylation of Rab25 promoter when Rab25 acts as a tumor suppressor, and vice versa, remains elusive." (PMID 28969096, 2017). "Investigations have indicated that Rab25 has been implicated in the succession of tumor by regulating the localization of integrin-recycling vesicles to develop tumor invasion." (PMID 25815277, 2015). "Changes in the localization of integrin β1, which affects tumor cell invasion/migration, have been associated with both increased and decreased RAB25." (PMID 24216980, 2013). "Patients with tumors expressing a low level of RAB25 had a higher risk of tumor recurrence, node or distant metastases, and death." (PMID 24403269, 2013). "The fourth patient, who had a low tumor expression of RAB25, died from a cause unrelated to the HNSCC." (PMID 24403269, 2013). "Again, CART analysis selected the 1.75 mRNA level as the best cut-off to classify patients in two risk groups: a high-risk group whose tumors expressed a RAB25 mRNA level below 1.75 and a low-risk group with a RAB25-tumor mRNA level above 1.75." (PMID 24403269, 2013). "Our findings showed that loss of RAB25 expression is a common event in HNSCCs and supported its role as a tumor suppressor." (PMID 24403269, 2013). "Recent studies of mouse models of intestinal and colonic neoplasia have demonstrated that Rab25 deficiency markedly promotes the development of neoplasia." (PMID 21063400, 2011). "Chia and Tang have reported that Rab25 is important in epithelial tumor progression and aggressiveness, associating with α5β1 integrin to increase tumor cell invasion." (PMID 21143914, 2010). "Our findings reveal that RAB25 functions as a tumor suppressor gene, and loss of RAB25 could serve as a novel biomarker of the claudin-low type of TNBC." (PMID 38803515, 2024). "In addition, we found that the integrated value for RAB25 amplification and the known tumor marker CA125 was associated with EOC patient prognosis." (PMID 36672479, 2023). "A high expression of RAB25 in pretreatment tumor biopsies reduced the risk of patient death." (PMID 24403269, 2013). "In summary, we have shown loss of RAB25 expression in tumor samples, an association between low RAB25 expression and poor clinical outcome, and a reduction in cell migration and increased sensitivity to cisplatin sensitivity in RAB25 overexpressing cells." (PMID 24403269, 2013). "We observed a loss of RAB25 tumor expression in all four sets of samples analyzed." (PMID 24403269, 2013). "Loss of RAB25 expression could therefore increase the invasion and dissemination ability of tumor cells in patients, and consequently increase the risk of recurrences and development of lymph node or distant metastases." (PMID 24403269, 2013). "Loss of Rab25 is associated with tumor initiation in the colon and ER-negative breast cancer." (PMID 22197222, 2012). "However, whether suppression of β1 integrin recycling contributed to reduction of tumor formation in Rab25-deficient mice and the mechanisms involved have to be further investigated." (PMID 28969096, 2017).
tumor (continued). "Rab25-driven tumor cell invasion into fibronectin (FN)-rich CDMs is highly dependent on Rab25’s ability to interact with integrin β1–containing recycling vesicles." (PMID 40614209, 2025). "We further used Western Blot experiment to verify the expression of Rab25 in tumor tissues of each group." (PMID 39196297, 2024). "Markers such as N-cadherin, vimentin, and fibronectin rose in the transformed clones, implying that the combination of loss of RAB25 and H-RAS61L overexpression was driving immortal HMEC toward a mesenchymal-like, stem cell-enriched tumor." (PMID 38803515, 2024). "We also looked at the expression of RAB25 and Snail in mouse tumor sections by immunohistochemistry." (PMID 38803515, 2024). "A series of Rab GTPases such as Rab1, Rab3, Rab8, Rab25, Rab27 and others promote cancer cells migration and invasion to exert critical infuences on tumor progression through mediating intracellular signaling pathways." (PMID 38695990, 2024). "Several molecular processes are involved in this mechanism of tumor cell resistance, namely Ras-related protein Rab-25 (RAB25) small GTPase, integrin members, and leucine rich repeat containing 15 (LRRC15)." (PMID 38068912, 2023). "The expression of miR-185-3p and RAB25 were also correlated with tumor grade and nodal metastasis stratification." (PMID 34868916, 2021). "It demonstrated that overexpression of miR-185-3p or knockdown of RAB25 increased tumor growth in vivo." (PMID 34868916, 2021). "Next, the expression levels of miR-185-3p and RAB25 in HNSCC tumor tissues were investigated using qRT-PCR." (PMID 34868916, 2021). "It is worth noting that Rab25 is also involved in the cell movement of epithelial cells, such as transformation and motility, which are correlated to tumor progression." (PMID 34440135, 2021). "Respectively, the expression of CDO1, CELF2, ITPRIPL1, KCNH8, RIC3, USP44 and ZSCAN23 was significantly lower in tumor tissues, whereas the expression of PTK6 and RAB25 was significantly higher in tumor tissues." (PMID 34056873, 2021). "Targeting miR-185-3p/RAB25 significantly inhibited tumor growth and promoted drug response to chemotherapy." (PMID 34868916, 2021). "IHC also showed an increased level of RAB25 expression in tumor tissues of miR-185-3p inhibitor-treated and combination treatment groups, confirming the anti-tumor effects of miR-185-3p inhibitor." (PMID 34868916, 2021). "Previous studies demonstrate that miR-577 is a well-recognized tumor suppressor and it negatively regulates a lot of oncogenes and oncogenic pathways, including Sphk2, Smurf1, Rab14, Rab25, LRP6, β-catenin, Wnt2b, and so on." (PMID 33069244, 2020). "As an oncogene or tumour suppressor, the reported roles of Rab25 are diverse in existing publications." (PMID 30848009, 2019). "Although the reproducibility of particular edges in the ensemble of Bayesian networks was relatively low for the cell line data, the connection from Claudin7 to Rab25 was present in 48% of the networks, and in all the networks inferred from tumor samples." (PMID 29293502, 2018). "Rab25 contributes to tumor progression by directing the localization of integrin-recycling vesicles and thereby enhancing the ability of tumor cells to invade the extracellular matrix." (PMID 28969096, 2017). "Numerous studies have shown that RAB25, a rab superfamily protein of small GTPases, acts as a tumor suppressor or an oncogene in the tumorigenicity of several types of cancers." (PMID 29079774, 2017). "Rab25, an epithelial-specific isoform of the Rab11 subfamily, has been reported to act as both an oncogene and tumour suppressor gene in various cancers." (PMID 29285208, 2017). "The ability of Rab25 in cell growth stimulation and cell death suppression implicates the important role of Rab25 in supporting tumor growth." (PMID 28969096, 2017).
tumor (continued). "Several lines of evidence have indicated that RAB25 has a large impact on epithelial cell transformation, tumor motility and the invasive ability of several epithelial cancers." (PMID 28784136, 2017). "RAB25 is a known tumor suppressor gene, acting through multiple pathways to enhance apoptosis and suppress angiogenesis and invasion by modulating VEGF-A and VEGFR-1 expression." (PMID 26646320, 2016). "In the claudin-low lines the most robust anti tumor effect of Rab25 was observed during cell migration." (PMID 27259233, 2016). "Recently, a number of protein-coding genes, such as PTK6 and Rab25, have been identified as having tumor suppressor activity through modulating different signaling pathways." (PMID 26158411, 2015). "Another study suggested that RAB25, when combined with the chloride intracellular channel 3, regulates tumor invasiveness and mediates the recycling of α5β1-integrin to the plasma membrane from a late endosomal compartment." (PMID 25351113, 2015). "Recently, investigations have shown that Rab25 acts as a tumor suppressor in colon and oesophageal cancers, regulating cell adhesion, polarity and signalling pathways." (PMID 25815277, 2015). "This evidence indicates that RAB25 is crucial in determining tumor development, progression and aggressiveness." (PMID 25351113, 2015). "Several DEGs have been demonstrated to be associated with tumor development, including protease serine 8 (PRSS8), claudin 7 (CLDN7) and Ras-related protein Rab-25 (RAB25)." (PMID 25351113, 2015). "In a way reminiscent to Rab25, both the availability of regulators and effector would be important variables in determining if the Rab would be oncogenic, or conversely tumour suppressive." (PMID 25472813, 2015). "Rab25 has also been shown to function as a tumor suppressor in hormonally insensitive breast tumors where its expression is lost." (PMID 25815277, 2015). "Additional molecular studies are needed to further investigate the cooperation between Rab members, their effectors and established oncogenic events in order to reconcile discrepancies between tumor suppressors versus promoter activity of Rab25 in HNSCC." (PMID 26110570, 2015). "A high expression of Rab25 protein was significantly correlated with the primary tumor stage; lymph node metastasis; distant metastasis; tumor, node and metastasis stage and histological grade." (PMID 25187796, 2014). "This tumor subtype underexpressed RAB25, a small GTPase protein that plays a role in the recycling of internalized membrane proteins and in the regulation of epithelial cell polarity." (PMID 24403269, 2013). "Our findings support a tumor suppressor role for RAB25 in HNSCC and its potential use to identify locally advanced patients with a high probability of survival after genotoxic treatment." (PMID 24403269, 2013). "Studies published to date show that the role of RAB25 in tumorigenesis and patient prognosis depends on the tumor type and the cell of origin in which RAB25 is expressed." (PMID 24403269, 2013). "Three of these patients showed a high tumor expression of RAB25 and were alive at the end of the study." (PMID 24403269, 2013). "RAB25, an epithelial-specific member of the Rab family of small GTPases, can act both as a tumor promoter and suppressor." (PMID 24216980, 2013). "We prospectively analyzed RAB25 mRNA expression levels by quantitative RT-PCR in 117 pretreatment tumor biopsies obtained from patients with locally advanced HNSCC treated at the HSCSP." (PMID 24403269, 2013). "In the absence of CLIC3, RAB25 acts as a tumor suppressor, whereas in the presence of CLIC3, RAB25 increases tumor aggressiveness." (PMID 24216980, 2013). "Normal and hyperplasic epithelial tissue adjacent to the tumor were positive for RAB25 immunostaining." (PMID 24403269, 2013). "We found significant differences in RAB25 mRNA expression levels between tumor and mucosa tissues in all the analyzed datasets." (PMID 24403269, 2013).